CGAS (cyclic GMP-AMP synthase)
Diseases named in the same sentence as CGAS in open-access papers (continued):
Sharing a sentence is not in itself a finding about the gene and the disease.
Myocardial fibrosis (6 papers, 2024 to 2025). "At the same time, bulk of classical inflammatory pathways have been proven to contribute to cardiac dysfunction and myocardial fibrosis, such as cGAS-STING, SIRT3-FOS and cAMP-AMPK pathways." (PMID 40623816, 2025). "Extracellular mitochondria can also activate cGAS in cardiac fibroblasts, contributing to myocardial fibrosis in MI/R injury." (PMID 38243316, 2024). "C-MitoHF promoted myocardial fibrosis and hypertrophy, and cardiac systolic dysfunction in HF mice, which could be ameliorated by cGAS KD." (PMID 38243316, 2024). "All three types of exercise interventions effectively suppressed cGAS–STING pathway activity, reduced inflammation and PANoptosis, alleviated myocardial fibrosis, and improved cardiac function." (PMID 41008530, 2025). "This study demonstrated that DCM induced by HFD combined with STZ was characterized by activation of the cGAS–STING signaling pathway, accompanied by increased expression of inflammatory cytokines and PANoptosis-related genes, pronounced myocardial fibrosis, and impaired cardiac function." (PMID 41008530, 2025). "Our findings suggest that the cGAS–STING pathway may act as an upstream driver that activates downstream processes such as inflammation and PANoptosis, ultimately leading to myocardial fibrosis and impaired cardiac function." (PMID 41008530, 2025).
myocarditis (6 papers, 2023 to 2025). Myocarditis is a condition that is characterized by inflammation of the heart muscle (myocardium). "The therapeutic modulation of myocarditis through the activation or inhibition of the cGAS-STING pathway has shown promise in therapeutic applications." (PMID 40461989, 2025). "In summary, these data showed that in PA-induced myocardial inflammation, the released cytoplasmic mtDNA acted as the ligand of the cGAS-STING system." (PMID 35235096, 2023). "Taken together, these results indicated that activation of the cGAS-STING pathway is involved in PA-induced myocardial inflammation." (PMID 35235096, 2023). "Mechanically, pyroptosis-mediated by GSDME in cardiomyocytes facilitates ICIs-associated myocarditis via mediating mitochondrial damage and releasing mitochondrial DNA (mtDNA), further activating cyclic GMP-AMP synthase (cGAS)-stimulator of interferon genes (STING) signaling pathway." (PMID 41225509, 2025). "Additionally, the cGAS-STING signaling pathway is involved in the development of myocarditis." (PMID 39664570, 2024).
small cell lung carcinoma (6 papers, 2021 to 2025). Small cell lung cancer (SCLC) is a highly aggressive malignant neoplasm, accounting for 10-15% of lung cancer cases, characterized byrapid growth, and early metastasis. "Previous studies indicate that inhibiting RAD51‐mediated DNA repair in small cell lung cancer causes DNA damage accumulation, activating the cGAS‐STING pathway to promote CD8+ T‐cell infiltration and enhance PD‐1/PD‐L1 checkpoint inhibitor efficacy." (PMID 41350246, 2025). "Querying TCGA datasets led us to find that the cGAS gene is mutated (13 in 20 cases) in SCLC (small cell lung cancer) patients and deleted (23 in 237 cases) in metastatic breast cancer patients (the MBC project)." (PMID 33927185, 2021). "cGAS-STING mediated immunogenicity triggered by DNA damage has also been reported in breast and small cell lung cancer (SCLC)." (PMID 40445433, 2025). "Activation of the cGAS-STING pathway has been demonstrated to increase the expression of PD-L1 on the surface of tumor cells and thus attenuate the activity of CTLs, which has been confirmed in models of liver cancer, melanoma, non-small cell lung cancer (NSCLC) and small cell lung cancer (SCLC)." (PMID 36353640, 2022).
cognitive decline (5 papers, 2023 to 2026). "cGAS KO in the brains of AD mice with reduced Aβ levels and a better proportion of microglia near Aβ plaques suggests that deletion of cGAS promotes Aβ clearance by microglia and ameliorates AD-associated cognitive decline." (PMID 39114669, 2024). "Thus, we would expect that cGAS deficiency would partially protect mice fed a HFD from cognitive decline." (PMID 37206668, 2023). "This study uncovers a novel and systemic mechanism linking peripheral aging processes to brain dysfunction, highlighting plasma EV‐derived LINE‐1 RNA as a key driver of neuroinflammation and cognitive decline through activation of the cGAS‐STING pathway." (PMID 41480826, 2026). "Our findings position EV‐derived LINE‐1 RNA and its downstream cGAS‐STING pathway as critical systemic drivers of brain aging, presenting promising therapeutic targets for mitigating cognitive decline and age‐related neurodegenerative diseases." (PMID 41480826, 2026). "Plasma extracellular vesicle‐derived LINE‐1 RNA increases with age and crosses the blood–brain barrier to activate microglial cGAS‐STING signaling, driving neuroinflammation and cognitive decline." (PMID 41480826, 2026). "In conclusion, this study identifies EV‐derived LINE‐1 RNA as a central mediator of brain aging, providing mechanistic evidence to support that the EV‐derived LINE‐1 RNA activates the cGAS‐STING pathway to drive neuroinflammation and cognitive decline." (PMID 41480826, 2026). "Thus, the cGAS/STING signaling pathway is a significant driver of inflammaging, or age-related inflammation, in the peripheral organs and the brain that can be targeted to combat the neurodegeneration and cognitive decline associated with aging and seen in older people." (PMID 38339107, 2024). "Additionally, aging increases the cytosolic dsDNA released from perturbed mitochondria in old or aging microglia, which induces cGAS/STING signaling activation, triggering reactive microglial transcriptional states, neurodegeneration, and cognitive decline." (PMID 38339107, 2024). "We hypothesized that cGAS-/- mice would have reduced microglial activation, lower inflammation, and thus be partially protected from HFD-induced cognitive decline." (PMID 37206668, 2023).
colon adenocarcinoma (5 papers, 2020 to 2025). "A loss of cGAS-STING can also render mice more susceptible than WT mice to developing colitis-associated colonic adenocarcinoma when subjected to treatment with DNA damage-inducing agents." (PMID 32774773, 2020).
head and neck cancer (5 papers, 2022 to 2025). A primary or metastatic malignant neoplasm affecting the head and neck. "In summary, our comprehensive analysis of the STING pathway in head and neck cancers reveals a fundamental limitation of modeling this disease using HNSCC cell lines to investigate the cGAS-STING pathway." (PMID 38147007, 2024). "A new generation of therapies targeting the cGAS–STING signaling pathway, including STING agonists, have recently attracted interest regarding the antitumor role of cGAS–STING signaling in head and neck carcinomas." (PMID 37444620, 2023). "To determine whether the effects of cGAS were specific to etoposide, we treated cells with cisplatin a drug that is often used for treatment of head and neck cancers." (PMID 35877778, 2022).
hepatitis B virus infection (5 papers, 2021 to 2025). A viral infection caused by the hepatitis B virus. "Kyoto Encyclopedia of Genes and Genomes (KEGG) further confirmed the top down‐regulated pathway in cGas−/− microglia was Salmonella infection, Hepatitis B virus infection, and Epstein–Barr virus infection." (PMID 36914567, 2023). "In viral hepatitis B and HCC, the cGAS-STING signaling pathway plays an inhibitory role during disease progression, while in ALD and NAFLD, it plays a promoting role." (PMID 34483930, 2021).
leukemia (5 papers, 2023 to 2025). A malignant (clonal) hematologic disorder, involving hematopoietic stem cells and characterized by the presence of primitive or atypical myeloid or lymphoid cells in the bone marrow and the blood. "PLK4 inhibitor mediated senescence and upregulated cytokine response was ameliorated when leukemia cells were treated with cGAS or STING inhibitor." (PMID 40940791, 2025). "THP-1 cells, a human leukemia monocytic cell line, were utilized to assess the status of the cGAS-STING signaling pathway under SFTSV infection." (PMID 38712963, 2024). "The inhibitory effect of licorice extract on the cGAS-STING pathway was also confirmed in human leukemia monocytic cell line THP-1." (PMID 37081966, 2023). "Notably, leukemia cells express higher levels of cGAS relative to normal counterparts from healthy donors." (PMID 38413714, 2024). "However, inhibiting PRMT9 in AML can trigger an anti-leukemia immune response by activating the cGAS-STING pathway, suggesting that PRMT9 may play an immunosuppressive role in this context." (PMID 41154773, 2025). "This sets off the cGAS–STING pathway, which in turn sets off leukemia-specific immune reactions." (PMID 41154773, 2025).
Listeria monocytogenes infection (5 papers, 2017 to 2025). "It has also been observed that in Listeria monocytogenes infection, exosomes are loaded with bacterial DNA capable of activating signaling mediated by the cGAS-STING cytosolic DNA sensing pathway, activating the innate immune system response." (PMID 41246298, 2025). "Intriguingly, during Listeria monocytogenes infection,also bystander cells can be activated via the cGAS–STING pathway." (PMID 33715389, 2021). "Specifically, human IFI16 was shown to amplify the cGAS-STING canonical pathway to induce IFNβ in response to Listeria monocytogenes infection and the subsequent presence of bacterial DNA in the cytosol of human macrophages." (PMID 32922386, 2020). "In vertebrates, STING has been reported to be triggered by bacterial DNA-activated cGAS or another DNA sensor, IFI16, leading to the production of IFN-I during Listeria monocytogenes infection." (PMID 36059529, 2022).
lymphoma (5 papers, 2021 to 2025). A malignant (clonal) proliferation of B- lymphocytes or T- lymphocytes which involves the lymph nodes, bone marrow and/or extranodal sites. "Because elevated activation of the cGAS-STING pathway has been associated with peripheral T-cell lymphomas and we found the Top3b-KO mice to be immune-compromized, we used a lymphoma syngeneic model and compared tumor development in Top3b-KO and WT mice." (PMID 40568167, 2025). "mtDNA can enhance the function of Treg through the cGAS-STING signaling pathway, thereby suppressing tumor immunity and promoting the development of T lymphoma." (PMID 41246345, 2025). "In this study, we show that expression of STING, a key protein in the cGAS–STING immune response pathway, is restricted to lymphomas of T- and NK-cell origin and seems to be down regulated in B-cell NHLs." (PMID 35267494, 2022). "Nanocarriers (such as nanoparticles, liposomes, or viral particles) have improved the efficacy and delivery of molecules targeting cGAS-STING, used in the treatment of solid tumors, lymphomas or to potentiate influenza vaccine response." (PMID 33708225, 2021).
mastitis (5 papers, 2022 to 2025). Inflammation of breast tissue during lactation or postpartum due to an obstructed duct or infection. "Collectively, LP alleviates E. coli-associated mastitis by modulating gut microbiota through the gut–mammary axis and directly inhibiting the cGAS-STING/NF-κB axis, supported by multi-model evidence." (PMID 41302013, 2025). "In conclusion, our work delineates a novel pathway from HCD feeding to mastitis, centered on DNA-laden mEVs and the cGAS-STING pathway." (PMID 41466496, 2025). "To explore the mechanism by which LP mitigates mastitis, we examined its regulatory effects on the cGAS-STING signaling pathway." (PMID 41302013, 2025). "Our results demonstrate that both HCD-fed goats and HC-RMT mice exhibiting mastitis showed clear activation of the cGAS-STING pathway in mammary tissue." (PMID 41466496, 2025). "In summary, these findings suggest that SEV induces mastitis in mice, activates the cGAS-STING-NF-κB/NLRP3 pathway, and disrupts the integrity of the mammary barrier." (PMID 41466496, 2025). "Given that the cGAS-STING pathway recognizes pathogenic DNA and triggers inflammation, we hypothesized that LP could prevent mastitis in dairy cows by modulating the cellular cGAS-STING signaling pathway." (PMID 41302013, 2025). "Although some studies demonstrated the various effects of LP, it remains unclear whether LP exerts its anti-mastitis effects through the cGAS-STING signaling pathway." (PMID 41302013, 2025). "In conclusion, these results suggest that the cGAS-STING-NF-κB/NLRP3 signaling pathways is activated in both HCD-induced goats and HC-RMT mice, contributing to the development of mastitis." (PMID 41466496, 2025). "We propose that these mEVs reach the mammary gland, where their microbial DNA cargo activates the cGAS-STING pathway, subsequently triggering the NF-κB and NLRP3 inflammasome axes, ultimately inducing mastitis." (PMID 41466496, 2025). "Once there, these mEVs activate the cGAS-STING-NF-κB/NLRP3 signaling pathway, ultimately inducing mastitis." (PMID 41466496, 2025). "Using a combined pharmacological and genetic approach, we confirmed the pathway's necessity: the cGAS inhibitor RU.521 significantly reduced mEVs-induced inflammation, and STING −/− mice were largely protected from mEVs-triggered mastitis." (PMID 41466496, 2025). "Based on the previous findings, alterations in CMPK2 expression within mammary tissue were further investigated, revealing that Nia significantly inhibited the protein levels of CMPK2, cGAS/STING, and key executive proteins involved in PCDs in S. aureus‐induced mastitis in mice." (PMID 39792800, 2025).
pancreatic ductal adenocarcinoma (5 papers, 2023 to 2025). An infiltrating adenocarcinoma that arises from the epithelial cells of the pancreas. "For instance, increased TREX1 expression enables pancreatic ductal adenocarcinoma cells to evade immune detection by inhibiting the cGAS-STING pathway." (PMID 41346575, 2025). "Therefore, D166 provides superior activation of the cGAS-STING pathway in pancreatic ductal adenocarcinoma organoids compared with previously reported STING agonists." (PMID 40520004, 2025). "In pancreatic ductal adenocarcinoma, TSPAN7 inhibits RAD51AP1‐mediated DSB repair, activating cGAS‐STING signalling to increase CD8+ T‐cell infiltration and improve chemoimmunotherapy efficacy." (PMID 41350246, 2025). "In pancreatic ductal adenocarcinoma, a high-iron diet or GPX4 depletion promotes 8-OHG release, thereby activating the cyclic GMP-AMP synthase (cGAS)-stimulator of interferon (STING) pathway and resulting in macrophage infiltration and activation." (PMID 38065948, 2023).
sarcoma (5 papers, 2021 to 2026). A usually aggressive malignant neoplasm of the soft tissue or bone. "Herein, we demonstrated, for the first time, the enhanced antitumor activity of NK and CIK cells against sarcoma cells pretreated with the trabectedin-olaparib combination, as well as the loss of this efficacy when the cGAS-STING-IRF3-IFNβ pathway is impaired." (PMID 40986050, 2025). "We then tested whether Atrx deletion created a cellular environment or selective pressure in sarcomas favoring the accumulation of acquired mutations in the CGAS/STING pathway." (PMID 37200088, 2023). "We further showed that, in both human and mouse sarcoma models, Atrx loss-of-function mutation led to a deficiency in CGAS/STING signaling that could be therapeutically targeted by a mouse-specific variant of the FDA-approved oncolytic herpesvirus TVEC." (PMID 37200088, 2023). "We showed that IRF3 specifically binds to the POU5F1 promoter region and directly stimulates gene transcription in response to cGAS-STING pathway activation in sarcoma cells." (PMID 40986050, 2025). "Since activation of the cGAS–STING pathway enhanced NKG2DL expression in sarcoma cells following trabectedin–olaparib treatment, we next evaluated the antitumor activity of NK/CIK cells after drug exposure." (PMID 40986050, 2025). "Our work using both mouse and human sarcoma models extends these findings by showing that Atrx deletion impairs the CGAS/STING pathway and increases sarcoma susceptibility to oncolytic herpesvirus in vitro and in vivo." (PMID 37200088, 2023). "We then performed a series of qPCR experiments to confirm downregulation of the CGAS/STING pathway in Atrx-deleted sarcomas." (PMID 37200088, 2023). "Our findings demonstrate that Atrx deletion in both human and mouse sarcomas impaired CGAS/STING signaling response to dsDNA transfection in vitro and to radiation in vitro and in vivo." (PMID 37200088, 2023). "We further showed that Atrx-deleted primary sarcomas have impaired adaptive immune response and reduced tumor-intrinsic CGAS/STING signaling after radiation." (PMID 37200088, 2023). "We also stimulated the 143B isogenic cell lines with cGAMP and found that the 143B ATRX KO cell line had significantly less expression of IFNB1, suggesting that at least part of the CGAS/STING pathway impairment was occurring downstream of CGAS in our human sarcoma cell lines." (PMID 37200088, 2023). "It was unclear, however, whether impaired CGAS/STING signaling would be present in Atrx-deleted sarcomas and how radiation would alter this pathway in vitro and in vivo." (PMID 37200088, 2023). "Finally, we demonstrated that sarcomas with Atrx deletion and aberrant CGAS/STING signaling were sensitized to oncolytic herpesvirus therapy." (PMID 37200088, 2023). "We found that both human and mouse models of Atrx-deleted sarcoma had a reduced adaptive immune response, markedly impaired CGAS/STING signaling, and increased sensitivity to TVEC, an oncolytic herpesvirus that is currently FDA approved for the treatment of aggressive melanomas." (PMID 37200088, 2023). "This leads to activation of innate immune signaling via the cGAS/STING pathway, ultimately correlating with improved survival of sarcoma patients." (PMID 41735292, 2026). "Here, we showed that the perpetuation of DNA damage leads to the accumulation of cytosolic dsDNA, triggering the cGAS-STING pathway, activating the transcription factor IRF3, and eventually promoting IFNβ production in surviving sarcoma cells." (PMID 40986050, 2025). "We first tested the effect of transfection of dsDNA from HSV type I (HSV-60), a well described stimulant of CGAS/STING signaling, in 3 isogenic mouse sarcoma cell line pairs." (PMID 37200088, 2023). "While the cGAS-STING mechanism has been extensively studied in other tumors, not much is known about its activity in sarcomas." (PMID 34440251, 2021).
sarcoma (continued). "To test whether these findings also held true in human sarcomas, we used our isogenic 143B human sarcoma cell line with or without CRISPR ATRX knockout and assessed IFNB1 expression levels after treatment with oHSV-60, a 60-bp DNA sequence known to potently stimulate the CGAS/STING pathway." (PMID 37200088, 2023).
skin cutaneous melanoma (5 papers, 2022 to 2025). "A total of 448 skin cutaneous melanoma samples from the TCGA PanCancer Atlas were categorized into two groups based on their expression levels of cGAS: high and low." (PMID 38506049, 2024). "In initial survey of bioinformatics datasets for the pan-cancer mRNA expression profiles obtained from the TGCA-GTEx dataset, we found RSK2 and cGAS mRNA levels were upregulated in skin cutaneous melanoma (SKCM)." (PMID 39424777, 2024). "The fraction of micronuclei and nuclear blebs stained with anti-cGAS antibody was significantly higher in plantar melanoma than in skin melanoma." (PMID 35468978, 2022).